CXCL9 (C-X-C motif chemokine ligand 9)
Diseases named in the same sentence as CXCL9 in open-access papers (continued):
Sharing a sentence is not in itself a finding about the gene and the disease.
tumor (continued). "This study identified tumor microenvironment-related genes, including monokine induced by gamma interferon (MIG or CXCL9), E26 transformation-specific variant 7 (ETV7), guanylate binding protein 4 (GBP4), and CD3 epsilon chain (CD3E)." (PMID 34054929, 2021). "The literature has indicated that immunotherapy targeting PD-1 and CTLA-4 specifically increases CXCL9 and CXCL10 from tumor-associated macrophages in tumor tissues, whereas CXCL9 and CXCL10 are induced by IFNγ in the tumor microenvironment." (PMID 34680466, 2021). "Many reports have confirmed that tumor-derived CXCL9 is a tumor suppressor 116, and is associated with a good prognosis and a good response to chemotherapy 124-126." (PMID 33854600, 2021). "A large recent meta-analysis concluded that a compound signature involving tumor mutational burden, CXCL9, UV, APOBEC, and tobacco signatures can identify pan-cancer responses to ICB." (PMID 34534438, 2021). "Higher tumor-infiltrating B-cells in HPV-associated oropharyngeal squamous cell carcinoma were associated with high CXCL9 production and high levels of tumor-infiltrating CD8 T-cells." (PMID 34692696, 2021). "Immunostaining on TMA of tumor samples showed that high CXCL9 protein expression in TAM was indeed associated with higher expression of CXCL9 mRNA by TAMs (ie, presence of M1hot TAMs) and a greater CD8+ T-cell density." (PMID 32699181, 2020). "For example, upregulation of CXCL9 or CXCL10 is associated with increased tumor infiltrating CD8+ T cells and natural killer cells." (PMID 33062639, 2020). "We found that all tumor-associated myeloid cell subsets analyzed (macrophages, monocyte-derived DC and cDC1) produce CXCL9 in vivo." (PMID 32461349, 2020). "FIP200 deletion induced an anti-tumor immune response mediated by CD8+ and CD4+ T cell infiltration to the tumor site, mediated by IFNγ and chemokine secretion (CXCL9, CXCL10, CXCL11) by autophagy-deficient tumor cells." (PMID 31554173, 2019). "High density of TIL-Bs was associated with an activated B cell phenotype, high CXCL9 production and high levels of tumor-infiltrating CD8+ T cells." (PMID 31623665, 2019). "We observe that the blockade of LIF in tumors expressing high levels of LIF decreases CD206, CD163 and CCL2 and induces CXCL9 expression in tumor-associated macrophages." (PMID 31186412, 2019). "Altogether, these results suggest that Sipa1−/− MSCs exhibit enhanced migration directed to Bcr-Abl+ cells and secretion of Cxcl9, which causes efficient recruitment of Sipa1−/− memory T cells to the vicinity of the tumor cells." (PMID 29500416, 2018). "When expressed on tumour cells CXCR3-A is pathogenic, interacting with CXCL-9 to promote tumour migration and invasion via the activation of phosphatidylinostol 3-kinase (PI3K) and mitogen activated protein kinase (MAPK) signalling pathways." (PMID 29157300, 2017). "Tumours grown in PD-L1-deficient hosts were characterized by cytokines directly supporting lymphocyte infiltration such as CXCL9/10." (PMID 28220772, 2017). "Many other studies have delineated that CXCL9 was probably involved in tumor‐associated macrophages polarization 84, tumor cell motility 85, and the survival of H‐RS cells." (PMID 27726306, 2016). "CXCL9 has a versatile and controversial role in tumors, and accumulating evidence suggests that CXCL9 is closely associated with the prognosis of tumor patients." (PMID 27726306, 2016). "In ovarian cancer, synergistic effect of tumor‐associated IL‐17 and Th17 cells 66, as well as IL‐18‐primed “helper” NK cells 67, induced the production of endogenous CXCL9 and CXCL10 that were directly correlated with tumor‐infiltrating CD8+ T cells." (PMID 27726306, 2016). "CXCL9 was also induced in the metronomic CPA-treated tumor cells in association with other extracellular immune activators: TNFSF4, MICB, interleukins IL12, IL15, IL23, and IL17RB, and interferon response genes." (PMID 25952672, 2015).
tumor (continued). "In particular, this study identified CXCL9/Mig to be strongly associated with intra-tumor lymphocytic infiltrate and better responsiveness in all cohorts of patients studied." (PMID 21875439, 2011). "This study addresses the limitations of the traditional M1/M2 binary classification for tumor-associated macrophages (TAMs) in non-small cell lung cancer (NSCLC) by introducing a NSCLC-specific functional framework based on the CXCL9/SPP1 (CS) expression ratio." (PMID 42079623, 2026). "A recent study has shown that LIF regulates CD8+ T cell tumor infiltration by repressing CXCL9 expression in tumor-associated macrophages, and blocking LIF enhances T cell infiltration, improving responses to anti-PD1 therapy in glioblastoma and ovarian cancer models." (PMID 39857986, 2025). "Future work dissecting how additional epigenetic mechanisms might regulate age-associated Cxcl9/10 expression changes in tumor cells, such as DNA methylation and histone modifications, will be critical to fully understand how aging shapes the cancer epigenome." (PMID 41332581, 2025). "In addition, using the TCGA database, we observed that gene signature of IFN‐Mac_CXCL9 was associated with better prognosis, likely due to their capability to recruit T cells and exert anti‐tumour effects." (PMID 41275425, 2025). "However, while the paracrine effects of chemokines released by macrophages recruit anti-tumor immune cells, the autocrine effects of the CXCL9/10/11-CXCR3 axis within tumor cells are linked to increased tumor growth and metastatic potential." (PMID 40867314, 2025). "In addition, a subset of tumour‐associated macrophages expressing CD206 has also been reported to express CXCL9 and to play a role in supporting the presence of cDC1s, CD8+ T cells, and NK cells." (PMID 40745918, 2025). "However, when secreted by tumor associated-dendritic cells (TADCs), CXCL9 can also enhance the expression of the checkpoint molecule ligand programmed death-ligand 1 (PD-L1), thereby attenuating anti-tumor T cell immunity via the PD-1/PD-L1 pathway." (PMID 39114657, 2024). "As multiple myeloid populations within the TME express the ligand CXCL9, including both DCs and tumor-associated macrophages (TAMs), and these chemokines are broadly induced in response to treatment, it remains another avenue to investigate in the maintenance of TSL within TLSs." (PMID 39211052, 2024). "CXCL9 is associated with tumor density and MKI67 expression." (PMID 39009698, 2024). "Conversely, tumor-associated dendritic cells (TADCs) produce significantly higher levels of CXCL9." (PMID 39409924, 2024). "Additionally, CXCL9+tumor-associated macrophages exhibited a functional role in response to immune checkpoint therapy, indicating enhanced immune activation, effector memory, cytotoxic function, and reduced immunosuppressive cell subsets in treated tumors." (PMID 39349061, 2024). "However, tumor-associated macrophages (TAMs) can also express CXCL9 and recruit T cells to the tumor microenvironment." (PMID 38928238, 2024). "Given that CXCR3 is the concomitant receptor for CXCL9, we leveraged our scRNAseq data to assess which tumor-associated immune cells could interact with our AAV encoded transgene." (PMID 38997283, 2024). "Consistently, blocking CXCL9 or IFNγ stimulates tumor growth in mice with myeloid SHP-2 deficiency." (PMID 38022587, 2023). "Additionally, high levels of CXCL9+ cell infiltration were associated with the high level of PD-L1+ cells, which were expressed primarily at the junction between tumor cells and stroma." (PMID 36845675, 2023). "In fact, in the TME, many such as tumor-specific expression of CCL5 in conjunction with CXCL9 can enhance lymphocyte infiltration whereas the deficiency of these genes can also promote M2 macrophage differentiation, resulting in immune suppression and poor prognosis." (PMID 38143770, 2023).
tumor (continued). "The failure to attract tumour-reactive T cells to the tumour could be caused by the lack of appropriate chemokine secretion from the tumor (e.g. the down regulation of CXCL9 prevents CD8+ T cell tumor-infiltration." (PMID 36016946, 2022). "However, we noticed a small but significant decrease of F4/80-positive tumour-associated macrophages in Cxcl9+ tumours (median 60.2% vs. 74.5%; P = 0.04)." (PMID 35314795, 2022). "Overexpression of CXCL9 is associated with tumor progression." (PMID 35514751, 2022). "Association of CXCL9 mRNA expression levels in tumor with clinicopathologic characteristics." (PMID 34539647, 2021). "For example, whole exome and transcriptomic analysis of >1000 tumors treated with immune checkpoint inhibitors (across seven tumor types) showed that an elevated clonal tumor mutational burden, coupled with increased expression of CXCL9 (an IFN-inducible gene), is predictive of superior response." (PMID 33807608, 2021). "This meta-analysis study revealed the importance of both tumor-cell-intrinsic (e.g., tumor mutational burden and PD-L1 expression) and tumor-cell-extrinsic (e.g., CXCL9, CD8A, CXCL13, CCR5 and T cell inflamed gene expression signature) factors underpinning ICB sensitization." (PMID 34092233, 2021). "The CXCL9 mRNA level was found to be significantly higher in BC than in normal tissue and was associated with better survival outcomes in patients with ER-negative tumours." (PMID 34527583, 2021). "Further substantiating this observation was the elevated expression of Cxcl9 and Gzmb in the primary tumors of Pik3cg−/− mice, which are respectively associated with chemotactic recruitment of lymphocytes and lymphocytic induction of tumor cytotoxicity." (PMID 33668795, 2021). "Notably, the high expression of CXCL9 in tumor tissues was associated with enhanced CD8+ T-cell infiltration and improved survival." (PMID 34539647, 2021). "To explore the association between DEX inhibited-tumor growth and accumulation of immune response-related cells, we measured the levels of Cxcl9, Cxcl10, Cd3e, Gzmb, and Ifng which are closely related to the recruitment, presence, and function of Th1 cells and CD8+ T cells in the TME." (PMID 32156004, 2020). "CXCL9 is implicated as a tumor suppressor, due to its ability to recruit CD8+ cells." (PMID 31894627, 2020). "We also show changes in DCs, where Siah2 loss increased expression of the IFNγ-induced chemokine Cxcl9, which recruits effector T cells to a tumor site, and concomitantly decreased expression of Ccl17 and Ccl22, chemokines that contribute to recruitment of Tregs to tumors." (PMID 31911617, 2020). "From these results, high expression levels of NK cell-activating receptors, activated T cell markers (PD-1, CXCR3, and especially IFNγ), and tumor's T cell recruitment-associated markers (IFNγ receptor, PD-L1, and CXCL9) were necessary for successful T cell infiltration and tumor killing." (PMID 32795913, 2020). "An increased mRNA for PD1, PD-L1 and CXCL9 being associated with a better prognosis may mirror the host–tumor interaction." (PMID 33003392, 2020). "quanTIseq analysis of 8000 tumor samples revealed that cytotoxic T cell infiltration is more strongly associated with the activation of the CXCR3/CXCL9 axis than with mutational load and that deconvolution-based cell scores have prognostic value in several solid cancers." (PMID 31126321, 2019). "Thus, our new data suggests that previously reported inhibition of tumor angiogenesis is a secondary effect caused by earlier infiltration with M1-polarized macrophages producing increased CXCL9 and CXCL10." (PMID 31831780, 2019). "Tumor associated macrophages (TAM) are also a source of CXCL9 and CXCL12." (PMID 30319638, 2018). "Moreover, expression of CXCL9 has been associated with tumor‐infiltrating lymphocytes (TILs) and response to neoadjuvant chemotherapy in BC." (PMID 30019538, 2018).
tumor (continued). "E7046 + E7777 treatment activated the innate immune system which led to an “inflamed” TME evidenced by expression of genes encoding Ccl5/RANTES, macrophage inflammatory protein-1α (MIP-1α/Ccl3), Cxcl9, Cxcl10, and Cxcl11, previously found associated with tumor destruction." (PMID 28920002, 2017). "Our study demonstrated that CXCL9 is associated with tumor burden and aggressiveness of NPC tumors and the serum level of this ligand may be useful as a prognostic indicator." (PMID 24278236, 2013). "In addition, the higher CXCL9 serum levels were associated with pretreatment tumor stages, nodal stages, and overall stages." (PMID 24278236, 2013). "Notably, a study examining tumor‐associated macrophages in lung cancer patients revealed varying expressions of genes associated with inflammatory macrophages, specifically highlighting CXCL9, CXCL10, and Stat1 in relation to an “M1hot” phenotype." (PMID 38434763, 2024). "In addition, high level of CXCL9+ tumor-associated macrophages (TAMs) was associated with favorable prognosis, implying that this subpopulation of macrophage may activate anti-tumor immune responses." (PMID 38533207, 2024). "Myeloid cell-derived CXCL9 generally mediates anti-tumor immunity by recruiting cytotoxic lymphocytes, whereas CXCL9 produced by stromal cells like cancer-associated fibroblasts often contributes to metastasis and immune evasion." (PMID 41766875, 2026). "Our analyses revealed that CXCL9+ macrophage-rich immune cell niches were accumulated in the tumor-liver invasive margin, where 2 subclasses of the CXCL9+ immune cell niches, CXCL9+TRAC+ (CT) and CXCL9+C1QB+ (CC) niches, were identified." (PMID 41766656, 2026). "Remarkably, DNA-methylation–induced silencing of immune effector genes was shown to impair T-cell trafficking to the tumor site by reducing tumor cell secretion CXCL9 and CXCL10." (PMID 39867570, 2025). "Recent research has highlighted that the CXCL9:SPP1 (CS) polarity dictates the anti-tumor or pro-tumor phenotype of TAMs." (PMID 40230843, 2025). "The methylation of these sites correlates with reduced expression of CXCL9 and CXCL10, which is associated with enhanced immune cell infiltration into the tumor microenvironment and a subsequent reduction in tumor growth." (PMID 39996888, 2025). "Subsequently, during the T cell trafficking phase (Step 4), activated T cells exit through efferent lymphatics, enter systemic circulation, and home to tumor sites guided by chemokine gradients (e.g., CXCL9/10)." (PMID 41281945, 2025). "Defining the molecular circuits governing these states, especially those regulating IL‐12p40 and CXCL9, will be essential to understanding cDC1 contributions to anti‐tumour immunity." (PMID 40745918, 2025). "A recent elegant study showed that immune evasion in ARID1A mutant tumours is mediated by impaired chromatin accessibility of IFNγ responsive genes, including Th1 chemokines CXCL9, CXCL10 and CXCL11." (PMID 39920335, 2025). "When interacting with CXCR3, CXCL9 promotes tumor growth and metastasis in certain contexts, but it also recruits immune cells like cytotoxic T-cells to the tumor, supporting anti-tumor immunity." (PMID 40362215, 2025). "Radiotherapy can also modulate the tumour microenvironment by increasing the expression of chemokines such as CXCL9 and CXCL10, which attract CAR-T cells to the tumour site." (PMID 40906384, 2025). "In a gene-level analysis, this pattern was consistent with the accumulation of Cd74+ and Cxcl9+ macrophages at the tumor edges and Spp1+ macrophages clustering toward the necrotic center." (PMID 41176316, 2025). "Within the tumor microenvironment, the formulation ensures controlled release of CXCL9, enhancing CD8+ T cell infiltration, while dBET6 triggers immunogenic cell death and inhibits IFNγ-induced PD-L1 expression to overcome immune evasion." (PMID 40284496, 2025). "Cxcl9 and Cxcl10 were specifically expressed in the Tumor-3 subcluster in the young, but much lower expressed in old." (PMID 41332581, 2025).
tumor (continued). "Together, these interactions enhance dendritic cell-mediated antigen cross-presentation and T-cell activation, with CXCL9/10-driven chemotaxis facilitating immune cell infiltration into the tumor." (PMID 40282455, 2025). "In multiple cancer types, elevated CXCL9/CXCR3 signaling has been associated with improved prognosis, primarily due to effective tumor-immune cell interactions that curb tumor progression." (PMID 40557143, 2025). "Inhibition of USP5 facilitates LC3-dependent intercellular transfer of P-STAT1/2 between tumor cells and macrophages, which thus elicits CXCL9+ macrophages and enhances radiation-induced antitumor immunity." (PMID 41321309, 2025). "Blocking PGE2 signaling restores functional CXCL9+CCR7neg cDC1s and improves tumor control, underscoring the role of PGE2 in disrupting local immune niches." (PMID 40667699, 2025). "The relative RNA expression demonstrated that Ccl5, Ccl8, Cxcl9, Cxcl10, Cxcl13 and Ccl21 were significantly higher in the 4MOSC1 tumours following oHSV therapy." (PMID 39219056, 2025). "The antitumor effect of IL-17 is synergistic with that of IFN-γ, which stimulates tumor cells to release the chemokines CXCL9 and CXCL10 to recruit NKs and CTLs into tumor sites." (PMID 40008144, 2025). "Overall, the flow cytometry analysis validated the scRNAseq data and showed that activated cDC1s and cDC2s within tumours can exist in two states, differentially expressing CXCL9 or CCR7." (PMID 40745918, 2025). "Proportionally, Cxcl9 cDC1s localised to a greater extent in the parenchyma (CytoMAP Region 6‐infTumour), while the Il12b cDC1s were enriched in tumour border regions (CytoMAP Region 5‐Border)." (PMID 40745918, 2025). "Reverse transcription quantitative PCR (RT-qPCR) analysis of tumor tissues unveiled a significant upregulation of several immune-related genes, including Ifng, Gzmb, Cxcl9 and Cxcl10." (PMID 40343532, 2025). "This study showed that HPTA treatment enhanced the recruitment of CD4+ T cells to tumor tissues, a process mediated by increased CXCL9/10 expression." (PMID 40040700, 2025). "This process requires the production of appropriate chemokines by the endothelial cells and tumor stroma, namely CXCL9, CXCL10, CXCL11, and CCL5." (PMID 41008910, 2025). "The anti-tumor effects of DB2313 were abolished by depleting macrophages with clodronate or inhibiting the CXCL9-CXCR3 chemokine axis using CXCL9- or CXCR3-neutralizing antibodies." (PMID 40867314, 2025). "To identify the association of Cxcl9 and Il12b cDC1s with TCF1+ CD8+ T cells, we generated masks representing areas where TCF1+ CD8+ T cells densely accumulate within tumours." (PMID 40745918, 2025). "M1 macrophages are usually recognized by the expression of CD86 and CD64 and by the production of CXCL9, which are indicative of their pro-inflammatory and anti-tumor activity." (PMID 39858472, 2025). "Functional enrichment analysis confirmed that tumour‐infiltrating IFN‐Mac_CXCL9 participates in MHC class II protein complex assembly and positively regulating lymphocyte activation." (PMID 41275425, 2025). "In line with a recent report that CXCL9 and SPP1 indicate tumor-associated macrophage polarity in human cancers, Cxcl9 expression was significantly higher in Trem2− macrophages, whereas Spp1 expression was significantly upregulated in Trem2+ macrophages." (PMID 39838454, 2025). "These nanovesicles were found to reprogram tumor-associated macrophages by shifting their polarization from the pro-tumor M2 phenotype, thereby enhancing the secretion of chemokines CCL5 and CXCL9." (PMID 40867539, 2025). "On the other hand, CXCL9 + macrophages can also directly interact with tumor cells, including releasing cytokines or remodeling the extracellular matrix environment." (PMID 41325308, 2025). "Norepinephrine decreased the secretion of CXCL9 (an inducer of CD8+ T cell infiltration) by tumor cells through the β-adrenergic receptor/WNT7A/β-catenin signaling pathway, thereby reducing CD8+ T cell infiltration." (PMID 40141195, 2025).